GTF3C2 (general transcription factor IIIC subunit 2)
Description:
Required for RNA polymerase III-mediated transcription. Component of TFIIIC that initiates transcription complex assembly on tRNA and is required for transcription of 5S rRNA and other stable nuclear and cytoplasmic RNAs. May play a direct role in stabilizing interactions of TFIIIC2 with TFIIIC1.
Synonyms: TFIIIC110; KIAA0011; TF3C-beta; TFIIIC-BETA
Tractability: PROTAC: ubiquitination databases record sites on it; its protein half-life has been measured.
Gene: Protein-coding gene on chromosome 2 (27,324,198 to 27,357,187, reverse strand). Ensembl gene ENSG00000115207.
Subcellular location: Nucleus
Subcellular location (Human Protein Atlas): Nucleoplasm
Pathways (Reactome):
Gene expression (Transcription): RNA Polymerase III Abortive And Retractive Initiation; RNA Polymerase III Transcription Initiation From Type 1 Promoter; RNA Polymerase III Transcription Initiation From Type 2 Promoter
Gene Ontology:
Molecular function: DNA binding; protein binding; RNA polymerase III general transcription initiation factor activity; RNA polymerase III type 1 promoter sequence-specific DNA binding
Biological process: transcription by RNA polymerase III; transcription initiation at RNA polymerase III promoter; 5S class rRNA transcription by RNA polymerase III; tRNA transcription by RNA polymerase III
Cellular component: nucleoplasm; nucleus; transcription factor TFIIIC complex
Genetic constraint (gnomAD): Loss-of-function variants: 8 observed, 65.64 expected, observed/expected ratio (o/e) 0.12, 90% interval 0.071 to 0.22. The upper end of that interval is the gene's LOEUF score, 0.22, which puts it in group 1 of 6, group 1 being the genes least tolerant of losing a copy. Missense variants: 605 observed, 801.89 expected, observed/expected ratio (o/e) 0.75, 90% interval 0.7 to 0.81. Synonymous variants: 320 observed, 315.31 expected, observed/expected ratio (o/e) 1.01, 90% interval 0.93 to 1.11.
Homologues: Orthologues: chimpanzee GTF3C2 (100% identical), macaque GTF3C2 (99% identical), dog GTF3C2 (94% identical), rabbit GTF3C2 (91% identical), guinea pig GTF3C2 (90% identical), pig GTF3C2 (89% identical), mouse Gtf3c2 (88% identical), rat Gtf3c2 (88% identical), tropical clawed frog gtf3c2 (44% identical), zebrafish gtf3c2 (35% identical).
Diseases named in the same sentence as GTF3C2 in open-access papers:
GTF3C2 is named in the same sentence as 14 diseases in open-access papers, as found by Europe PMC text mining. Sharing a sentence is not in itself a finding about the gene and the disease. The quoted sentences say what the papers report.
leukemia (2 papers, 2021). A malignant (clonal) hematologic disorder, involving hematopoietic stem cells and characterized by the presence of primitive or atypical myeloid or lymphoid cells in the bone marrow and the blood. "Among all GTF3 members, GTF3A was particularly highly expressed in CRC compared to normal tissues, whereas GTF3B, GTF3C1, and GTF3C2 had low expression levels in other types of cancers such as brain and central nervous system cancers, esophageal cancer, and leukemia." (PMID 33925358, 2021). "Compared to healthy BMMCs, we observed the TF networks of ZNF266, RORA, GTF3C2, ZNF76, ZNF383, IRF5 and NFE2L2 being top upregulated in all leukemia patients." (PMID 33408321, 2021).
liver cancer (1 paper, 2022). An epithelial or non-epithelial malignant neoplasm that arises from the liver. "GTF3C2 is one member of the general transcription factor III family, which has been reported as a prognostic factor in liver cancer." (PMID 36045381, 2022).
tumor (3 papers, 2021 to 2025). "In contrast, the expression levels of GTF3B, GTF3C1, and GTF3C2 in CRC were lower in tumor tissue compared to normal tissues." (PMID 33925358, 2021).
endocrinopathies (1 paper, 2014). "One of these variants, the N309K mutation in the PCSK1 gene, appeared to be the probable cause of the CDD and endocrinopathies, given that other mutations in PCSK1 are known to cause similar symptoms, whereas the other three variants (HADHA, FBXL17 and GTF3C2) are not known to be involved in CDD." (PMID 25272002, 2014).
infection (1 paper, 2017). The state of being infected such as from the introduction of a foreign agent such as serum, vaccine, antigenic substance or organism. "Unlike GTF3C2, we found that the expression of GFT3C4 (general transcription factor IIIC subunit 4) was not affected by WT infection." (PMID 29207503, 2017).
GTF3C2 also shares sentences with these, for which no sentence is quoted: cancer (3 papers); breast carcinoma (1); central nervous system cancer (1); dyslipidemia (1); esophageal cancer (1); Hyperglycemia (1); Obesity (1); renal carcinoma (1); type 2 diabetes (1).